EGFR (epidermal growth factor receptor)
Diseases named in the same sentence as EGFR in open-access papers (continued):
Sharing a sentence is not in itself a finding about the gene and the disease.
head and neck cancer (continued). "A pivotal study reported a benefit in overall survival and locoregional control in patients with localised head and neck cancer who were treated with both radiation and cetuximab, a monoclonal antibody against epidermal growth factor receptor (EGFR), over patients treated with radiation alone." (PMID 20628392, 2010). "Nearly all head and neck cancer expresses EGFR and it is correlated to an unfavorable prognosis." (PMID 20470428, 2010). "Our findings are comparable to results recently published of Korean, Austrian, and Spanish patient populations and we conclude that exon 19 and 21 EGFR mutations are not more common in head and neck cancer than in nonsmall-cell carcinoma." (PMID 20130810, 2009). "Surgery and radiotherapy are the most commonly used lines of treatment and currently the only approved molecular targeted therapy for head and neck cancer is cetuximab (Erbitux; ImClone Systems Inc., New York, NY), a monoclonal antibody inhibitor of epidermal growth factor receptor (EGFR)." (PMID 19721715, 2009). "Epidermal growth factor receptor is also implicated in angiogenesis, ability to metastasise, and inhibition of apoptosis Indeed, EGFR expression has been found to relate closely to prognosis in head and neck cancer, higher levels correlating with poorer progression-free and overall survival." (PMID 16495923, 2006). "Thus, inhibition of EGFR represents a potential therapeutic strategy for controlling cancer growth, particularly in head and neck cancer where the expression of this receptor is frequently amplified." (PMID 11986789, 2002). "PIT for advanced or locoregionally recurrent unresectable head and neck cancer (HNC-PIT) is a recently applied local method that targets EGFR on the surface of cancer cells, and although PIT for NPSCC has been practiced in Japan since September 2020, the results remain unclear." (PMID 40574027, 2025). "Especially, EGFR is more highly overexpressed (80–90%) in head and neck cancers (HNCs) than in any other cancer types, and this overexpression is strongly associated with a poor prognosis of HNC patients, suggesting that EGFR-targeted therapy may be a significant interest in HNC." (PMID 38888847, 2025). "For example, the EGFR signaling pathway is frequently abnormally active in head and neck cancer; its effects may be partly mediated by interfering with MOB1-dependent LATS1/2 activation in synergy with TAO kinase upregulation, collectively promoting YAP/TAZ activation." (PMID 40486910, 2025). "Conversely, pancreatic and head/neck cancers showed detrimental outcomes (HR=1.70-1.82), potentially due to their β1-AR dominance (60-75% of cases) which may trigger compensatory EGFR activation when blocked, compounded by dense stromal barriers limiting drug penetration." (PMID 40842986, 2025). "Importantly, the EGFR signaling might play an important role in the resistance of head and neck cancer to cisplatin." (PMID 34828441, 2021). "Since high EGFR expression is a negative prognostic factor, associated with lower progression-free and overall survival rates, we reasoned that resistant head and neck cancer cells could be re-sensitized to ionizing radiation by targeting EGFR and mTOR with cetuximab and rapamycin, respectively." (PMID 31640284, 2019). "Besides, higher tumor-to-colon and tumor-to-lung, as well as tumor-to-salivary gland and tumor-to-muscle ratios may improve imaging of primary colorectal, lung, and head-and-neck cancers, where elevated expression of EGFR has prognostic and predictive value." (PMID 30231504, 2018). "Interestingly, EGFR signaling not only induces de novo expression of PD-L1 as shown in lung and head and neck cancer but also promotes stabilization of PD-L1 surface expression through glycosylation of its extracellular domain mediated by glycogen synthase kinase 3β (GSK3β) activation." (PMID 28611673, 2017).
head and neck cancer (continued). "In head and neck cancer resistance of tumour cells to radiotherapy has been shown to increase proportionally with EGFR expression, and it has been proposed that up-regulation of EGFR is a mechanism employed by cancer cells to circumvent the cytotoxic effects of radiotherapy." (PMID 29069805, 2017). "Whether SphK1 is directly involved in activation of EGFR in head and neck cancer is unknown." (PMID 24970177, 2013). "Therapies such as the use of o-phenanthroline, or alternative approaches such as the use of small molecule EGFR tyrosine kinase inhibitors that block the intracellular tyrosine kinase domain, could hold great potential for the treatment of head and neck cancer." (PMID 21822357, 2011). "Thus, EGFR has become heavily targeted as a cancer therapeutic strategy, and this has improved response rates, locoregional control, and overall survival in combination with radiation in head and neck cancer patients." (PMID 21912620, 2011). "Cetuximab, an antibody targeting the epidermal growth factor receptor (EGFR), is also used to treat patients with head and neck cancer." (PMID 40063100, 2025). "EGFR inhibitors have been used to treat a variety of solid-organ malignancies, including NSCLC, gastrointestinal malignancies, and head and neck cancers." (PMID 40013222, 2025). "Cetuximab, which targets the epidermal growth factor receptor (EGFR), has been approved and is routinely used in the treatment of various malignant tumors, such as head and neck cancer." (PMID 41562074, 2025). "This study investigates the role and effectiveness of the epidermal growth factor receptor (EGFR) tyrosine kinase inhibitor (TKI) in oral cancer, focusing on the clinical relevance of EGFR and myeloid cell leukemia-1 (Mcl-1) in head and neck cancers (HNCs)." (PMID 38888847, 2025). "In this review, we explored the significance of EGFR and MPS1 as therapeutic targets in head and neck cancer." (PMID 39339232, 2024). "These inhibitors have revolutionized oncology, providing targeted treatments for individuals affected by EGFR-driven malignancies, such as NSCLC and head and neck cancer." (PMID 38611728, 2024). "EGFR, a transmembrane glycoprotein, is highly expressed in 90% of HNSCC cases and is a strong prognostic indicator of head and neck cancer." (PMID 39183296, 2024). "A worldwide phase 3 clinical trial of ASP‐1929, an anti‐epidermal growth factor receptor (EGFR) antibody cetuximab conjugated with IR700, is ongoing in patients with recurrent or inoperable head and neck cancer (NCT03769506)." (PMID 36259134, 2023). "In head and neck cancer cell lines (MDA686LN, JHU022), resistance to EGFR inhibitor erlotinib was observed, and this resistance appeared to be propagated by the Src-dependent activation of the MET signaling pathway." (PMID 38201459, 2023). "The epidermal growth factor receptor (EGFR) is involved in different types of carcinoma (e.g., breast, lung, prostate, and head and neck cancer) and has been related to cancer progression and poor prognosis." (PMID 36851313, 2023). "Currently, a global clinical trial in phase 3 is underway to investigate the efficacy of ASP-1929, an mAb-IR700 that targets the epidermal growth factor receptor (EGFR), in patients with recurrent or inoperable head and neck cancer (NCT03769506)." (PMID 37444510, 2023). "Cetuximab: Cetuximab is a human–mouse chimeric IgG1 mAb against the epidermal growth factor receptor (EGFR), which is FDA approved for the treatment of colorectal and head and neck cancer." (PMID 36231109, 2022). "These associations were additionally supported in CRISPR k.o. of the EGFR or ERBB2 genes in skin, liver, and head-and-neck cancer." (PMID 35614096, 2022). "Cetuximab, an anti-epidermal growth factor receptor (EGFR) monoclonal antibody, conjugated to IRDye800CW (Cet-IRDye800) is the first molecular targeted antibody probe to be used for IGS in head and neck cancer patients." (PMID 35837101, 2022).
head and neck cancer (continued). "The receptor tyrosine kinase (RTK) epidermal growth factor receptor (EGFR) is overexpressed and an important therapeutic target in Head and Neck cancer (HNC)." (PMID 35461210, 2022). "In head and neck cancer, HON inhibits the EGFR signaling and increases the activity of the EGFR inhibitor erlotinib." (PMID 36601474, 2022). "Using the EGFR as a TAA model, the frequency of EGFR-specific CTLs was significantly correlated with the EGFR expression in head and neck cancer, strengthening the idea of targeting self-antigens as a TAA." (PMID 35062731, 2022). "Zebrafish were used to study cetuximab, a monoclonal antibody targeting the epidermal growth factor receptor (EGFR), for the treatment of colorectal and head and neck cancer." (PMID 35565373, 2022). "In HPV− head and neck cancers, angiogenesis appears mainly driven by independent effects of NOTCH1 and EGFR, and their impact on HSNCC progression appears complementary." (PMID 34944837, 2021). "Erlotinib, by inhibiting EGFR, induces metabolic oxidative stress through NOX4 in human head and neck cancer cells." (PMID 33920356, 2021). "The epidermal growth factor receptor (EGFR) is abnormally activated in epithelial cancers, including head and neck cancers." (PMID 34830871, 2021). "Recent studies have reported that C225, an anti-epidermal growth factor receptor (EGFR) monoclonal antibody, can, in combination with radiation, suppress STAT3 activation results in radiosensitization in head and neck cancer." (PMID 34502158, 2021). "In various cancer types, including Head and neck carcinomas, Amphiregulin (AREG) overexpression has been involved in therapeutic failure and resistance to anti-EGFR therapies or to vincristine, a microtubule-destabilising agent." (PMID 34290392, 2021). "The main downstream target of epidermal growth factor receptor (EGFR) signaling, PI3K/Akt, plays a significant role in radioresistance of head-and-neck cancer." (PMID 32605153, 2020). "In UT-SCC5 and SAS head and neck cancer cells, PARP1 has been shown to serve as a mediator of EGFR/MEK-dependent regulation of DNA double-strand breaks." (PMID 32093123, 2020). "In hepatocellular carcinoma and head and neck cancer, PTPRS regulated EGFR in EMT processes and drug resistance." (PMID 33163494, 2020). "AXL overexpression has been reported to induce resistance to the EGFR inhibitor cetuximab in NSCLC and head and neck cancer cell models." (PMID 33396393, 2020). "Cetuximab (ErbituxTM) is an antibody against human EGFR that is approved by the FDA and EMA to treat colorectal and late stage head and neck cancer." (PMID 31940973, 2020). "As an antibody drug, cetuximab, which is a mouse-human (IgG1) chimeric antibody against the epidermal growth factor receptor (EGFR), was approved for the treatment of head and neck cancer (HNC), including oral cancer." (PMID 32218834, 2020). "Most head and neck cancer (HNC) patients are resistant to cetuximab, an antibody against the epidermal growth factor receptor." (PMID 32028632, 2020). "In a study of head and neck cancer, HPSE was shown to induce the phosphorylation of STAT3 through Src and EGFR phosphorylation, leading to a poor clinical outcome." (PMID 33256730, 2020). "Some well-studied TAAs, epidermal growth factor receptor (EGFR, also known as ErbB-1 or HER1), carcinoembryonic antigen (CEA), mucin 1 (MUC1), human telomerase reverse transcriptase (hTERT), etc. are also expressed in head and neck cancers at high levels." (PMID 32942747, 2020). "This is performed by applying nimotuzumab, which shows a strong affinity to the epidermal growth factor receptor (EGFR), which is markedly often present in head and neck carcinomas." (PMID 33080800, 2020). "Yet, EGFR-FITC-SiO2-NPs and FITC-SiO2-NPs showed a great variance in binding to head and neck cancer cells in cell culture." (PMID 31561451, 2019).
head and neck cancer (continued). "Overexpression of EGFR is correlated with PD-L1 expression in head and neck cancers in a JAK2/STAT1-dependent manner, indicating a novel role for JAK2/STAT1 in EGFR-induced immune evasion." (PMID 31775797, 2019). "Recently, cetuximab, a mouse-human (IgG1) chimeric antibody against epidermal growth factor receptor (EGFR), was approved for treating head and neck cancer (HNC) including oral cancer." (PMID 29854293, 2018). "The enhanced expression of IL-1β after GW5074 treatment was related to an increased phosphorylation of MEK1 and ERK1/2, indirectly confirming that activation of EGFR-downstream MEK and ERK affect IFNγ/TNFα induced chemokine secretion in head and neck cancer." (PMID 30192802, 2018). "The Epidermal Growth Factor Receptor (EGFR) is selectively expressed on the surface of numerous tumours, such as non-small cell lung, ovarian, colorectal and head and neck carcinomas." (PMID 29552307, 2018). "The epidermal growth factor receptor (EGFR) aberrations over activate the PI3K/AKT/mTOR pathway and its irradiation induced activation also upregulates PIM1 in head and neck carcinoma." (PMID 29401696, 2018). "In preclinical animal models of head and neck cancer, optical imaging agents targeted against αvβ3 integrin, cathepsine B, metalloproteinases, PARP1, and EGFR have been investigated." (PMID 28039488, 2017). "In this study, we analyzed the immediate early molecular response of cetuximab on physical interactions between EGFR and Insulin growth factor 1 like receptor (IGF-1R) in head and neck cancer cells that are resistant to cetuximab." (PMID 27716204, 2016). "We also compared the radiosensitizing effects of veliparib to that of the anti-epidermal growth factor receptor (EGFR) monoclonal antibody cetuximab, another targeted agent which modifies DNA DSB repair and is FDA-approved for use in head and neck cancers." (PMID 26336991, 2015). "Overexpression of miR-7, a well-known regulator of EGFR expression, was shown to enhance the effect of an EGFR TKI, erlotinib, in a head and neck cancer model system." (PMID 26287249, 2015). "The present study suggests that the combination of inhibitors of EGFr and STAT-3 enhances the effects of radiation in head and neck cancer compared to the use of either agent alone." (PMID 26458879, 2015). "It is known that EGFR is over-expressed in majority of the HNSCC and its abolition is considered as a therapeutic effect of any drug in head and neck cancer clinically." (PMID 26020804, 2015). "Following decades of active research, only one class of targeted molecular agents, epidermal growth factor receptor (EGFR) inhibitors, have been approved for use in head and neck cancers." (PMID 25428177, 2014). "Nimotuzumab, an IgG that recognizes the epidermal growth factor receptor (EGF-R) overexpressed in some tumors, is used in the treatment of advanced head and neck cancer." (PMID 27379284, 2014). "Especially, cetuximab, a monoclonal antibody targeting EGFR, has been intensively studied as an anti-cancer agent approved by the FDA for treating head and neck cancer." (PMID 25438047, 2014). "For example, the EGFR inhibitor Erbitux is FDA-approved for colorectal and head and neck cancers, despite the fact that EGFR hyper-activation occurs in many cancer types." (PMID 24570398, 2014). "BB2R and BB3R stimulate ERK and EGFR phosphorylation by stimulating metalloproteases and the release of TGF-α in a c-Src-dependent manner in head and neck cancer cell (HNSCC) lines and NSCLC in an NADPH oxidase-dependent manner." (PMID 23434665, 2013). "Perhaps by blocking EGFR and/or HER-2 signaling pathway, we can increase the sensitivity of head and neck cancer cells to sorafenib." (PMID 23563900, 2013). "Inhibition of EGFR by the monoclonal antibody, cetuximab has been shown to improve PFS and OS when combined with chemotherapy in patients with advanced head and neck cancer." (PMID 23563900, 2013).
head and neck cancer (continued). "Human papillomavirus (HPV)-related head and neck cancer has been associated with an improved prognosis in patients treated with radiotherapy (RT) +/− chemotherapy (CT); however, RT combined with epidermal growth factor receptor (EGFR) inhibitors has not been fully studied in this group of patients." (PMID 23331666, 2013). "EGFR is a member of the ErbB family of tyrosine kinase receptors and is commonly up-regulated in non-small cell lung cancer (NSCLC), head and neck cancer, colorectal cancer and hepatocellular cancer." (PMID 23434665, 2013). "The epidermal growth factor receptor (EGFR)-targeting IgG1 monoclonal antibody, cetuximab, is a breakthrough in targeted therapy for head and neck cancers, especially among patients with recurrent or metastatic disease." (PMID 23209663, 2012). "As pointed out earlier, EGFR is over expressed in most of the HNSCC and its inhibition indicates therapeutic effect in head and neck cancer clinically." (PMID 23050025, 2012). "Since ~90% squamous cell carcinomas of the head and neck (SCCHN) over-express EGFR and SCCHN cell lines are sensitive to oncolytic reovirus, we conducted a detailed analysis of the effects of reovirus in 15 head and neck cancer cell lines." (PMID 22920673, 2012). "Interest in targeting the IGF-1R in HNSCC was bolstered by the observation that treatment of head and neck cancer cells with either IGF or EGF resulted in IGF-IR and EGFR heterodimerization." (PMID 21776391, 2011). "In this study, we investigated the specific inhibitory effect of EGFR TK inhibitor EKB-569 on the regulation of NFκB-dependent survival advantage and elucidated its influence in potentiating radiotherapy for head and neck cancers." (PMID 22242139, 2011). "Targeted therapies that block EGFR, Met, and IGF-1R signaling in head and neck cancers continue to show promising results in preclinical studies and clinical trials." (PMID 21776391, 2011). "Contemporarily, there is increasing evidence supporting the concomitant use of cetuximab, a monoclonal antibody against the epidermal growth factor receptor (EGFR), in addition to high-dose radiotherapy in primary treatment concepts of head and neck cancer." (PMID 18226196, 2008). "Among the several factors identified to date, Hb level, EGFR and VEGF are all regarded as candidate influences on the effects of chemoradiation in the treatment of head and neck cancers." (PMID 16670721, 2006). "Although several studies have found overexpression of epidermal growth factor receptor (EGFR) proteins EGFR and Her-2 in head and neck cancers, the clinical relevance of the finding varies." (PMID 12915878, 2003). "In both breast and head and neck cancers, in addition to resistance to anti-EGFR therapy, additional obstacles include a lack of reliable biomarkers for predicting therapeutic responsiveness." (PMID 40560045, 2025). "Moreover, the presence of the fusion has been shown to herald resistance to anti-EGFR drugs, not only in NSCLC, but also in head and neck cancer." (PMID 39387893, 2025). "Since 90% of head and neck cancers are of squamous cell type, we interested ourselves especially on 9 molecules expressed in this type of cancers: BphB4, Elf3, CEA, CK18, CK19, Ep-CAM, EGFR, PVA, SCCA, GAPDAH (reference gene)." (PMID 40168331, 2025). "Also, pan-HER, composed of a mixture of six monoclonal antibodies targeted against EGFR, HER2,and HER3, demonstrated antiproliferative and radiosensitizing impact in human lung and head and neck cancer." (PMID 40656957, 2025). "Regarding CellSearch, there is for now no specific kit for head and neck cancer but using an anti-EGFR antibody in addition to the epithelial kit makes the detection a possible option." (PMID 40168331, 2025).